NLRC5 (NLR family CARD domain containing 5)
Diseases named in the same sentence as NLRC5 in open-access papers (continued):
Sharing a sentence is not in itself a finding about the gene and the disease.
infection (29 papers, 2013 to 2025). The state of being infected such as from the introduction of a foreign agent such as serum, vaccine, antigenic substance or organism. "At 24 hpi, infection with LPAIV H7N2 caused a significant increase in NLRC5 mRNA expression relative to the housekeeping gene HMBS from 0.40 ± 0.057 times in mock-infected cells to 8.86 ±0.499 times in LPAIV-infected cells." (PMID 32509599, 2020). "Relative protein expression in cells infected with the H5N2 and the H7N2 caused a 1.5- and 1.8-fold increase in measured NLRC5 protein as compared to mock infection, respectively." (PMID 32509599, 2020). "The authors explained this by the observation of a partial defect in IL-1β production in Nlrc5-deficient mice upon infection." (PMID 24319445, 2013). "In conclusion, IFN-γ–STAT1–IRF1 signaling and NLRC5 co-activation are attenuated in ΔgntR8 infection, leading to reduced H-2Kb expression and compromised antigen presentation to CD8+T cells." (PMID 41235247, 2025). "The expression of Nlrc5 was significantly upregulated after PmHN01 and PmHN02 infection in our study, which indicated that the body inhibited the inflammatory response to P. multocida infection by enhancing the expression of Nlrc5." (PMID 36838365, 2023). "Studies using Nlrc5-deficient mice demonstrated that NLRC5 plays a critical role in CD8 cytotoxic T cell activation and protection against infection of intracellular pathogens such as Listeria monocytogenes or influenza A virus." (PMID 34782627, 2021). "This suggested that NLRC5 played an important role in CD8+ T cell expansion during intracellular pathogen infection." (PMID 34307322, 2021). "High ZIKV replication was observed as early as 12 h and peaked at 48 h after infection, similar to the expression of NLRC5 mRNA in primary cortical neurons of mice." (PMID 34220868, 2021). "In chicken cells, NLRC5 expression has been induced upon LPS stimulation and infection with avian influenza virus." (PMID 33536090, 2021). "NLRC5 was observed to be upregulated in each of the AIV infections compared with the PBS mock infection control." (PMID 32509599, 2020). "Infection with the HPAIV also resulted in an increase in NLRC5 mRNA as well as an increase in viral titer." (PMID 32509599, 2020). "We first observed that NLRC5 is strongly upregulated after infection in both chicken macrophages and chicken primary lung cells, demonstrating that AIV infection can effectively upregulate expression in various cells." (PMID 32509599, 2020). "For example, ~6-fold upregulation of NLRC5 mRNA and protein was observed in HeLa cells upon infection with Sendai virus, whereas in THP1 cells <2-fold upregulation was seen." (PMID 32509599, 2020). "In vitro infection studies using human airway epithelial cells suggest a biological role of NLRC5 in antiviral immunity toward influenza A virus (PR8)." (PMID 28261210, 2017). "Using various infection models, it was found that NLRC5 is required for inflammasome activation by bacterial PAMPs and crystals, but not pore-forming toxins." (PMID 28261210, 2017). "NLRC5 is an intracellular receptor involved in innate immune sensing; it is induced by interferons in case of pathogen infection." (PMID 26651482, 2015). "First, there are many negative regulators of IFN-I production, and we found that two were increased in expression at days 5 and 15 post-infection (NLRC5 and TRIM21)." (PMID 23737750, 2013). "Nonetheless, two studies clearly show that NLRC5 is important in the control of infection by Listeria monocytogenes, a Gram-positive motile bacterium that primarily infects monocytes and macrophages." (PMID 24319445, 2013). "Moreover, NLRC5 knockdown significantly reduced the IL-1β secretion of human myeloid cells and primary monocytes during infection." (PMID 34307322, 2021).
infection (continued). "In addition, we observed a strong positive correlation between the upregulation of NLRC5 and increasing AIV titers, a phenomenon also observed in human cell lines, suggesting that NLRC5 activation leads to a more productive infection across species." (PMID 32509599, 2020). "Most previous NLRC5 work has been limited to human and mouse cell-based infection systems." (PMID 32509599, 2020). "Induction of the MHC-I gene expression was also evidenced in our experimental model of infection by over-expression of NLRC5, a specific transcriptional activator of the MHC-I expression, induced by IFNγ through STAT1 activation, whose coding genes were observed also over-expressed in this study." (PMID 29391047, 2018). "During E30 infection, genes associated with the type I IFN signaling pathway (Isg15, Mx1, Mx2, Sp100, Ifit1, Ifit3, Ifih1, Irf7, Irf9, guanylate-binding proteins 2 [Gbp2], and Stat1) and defense response to viruses (Ddx58, Ddx60, Zbp1, Oas2, Nlrc5, and Eif2ak2) were significantly upregulated." (PMID 36147849, 2022). "Moreover, NLRC5 expression was upregulated in the mouse brain after WNV NY99 infection, suggesting that neurotropic virus invading the CNS could induce the expression of NLRC5 in the brain of mice." (PMID 34220868, 2021). "Moreover, we showed that the infection of mice deficient in NLRC2 but not NLRC5 led to a reduction in parasite burden and lesion size." (PMID 29487860, 2018). "Many negative regulators, such as Tetherin, NLRC5, NLRP11, and RTP4, are induced after infection, to feedback and inhibit the production of IFNs." (PMID 37366613, 2023). "In summary, during infection with Pm HN01 and Pm HN02, genes related to immune inflammation, such as Nod2 and Nlrc5, were generally upregulated and significantly activated the NOD-like receptor signaling pathway." (PMID 36838365, 2023). "Common PRRs of NOD1, NOD2, NLRP3, NLRC4, NLRC5, and AIM2 were detected using qPCR assays after 90 min of infection with A. sobria at a MOI of 10 and 2 h gentamycin treatment followed by 12 h incubation." (PMID 34513725, 2021). "For instance, RNF125, IFI35, NLRC5, USP25, and A20 have been shown to negatively regulate RIG-I-induced antiviral signaling upon pathogen infection." (PMID 33584728, 2020). "We found that LgyLRV1+ infection, or poly(I:C) treated macrophages, up-regulate the inflammasome independent NLRs: NLRC2 and NLRC5." (PMID 29487860, 2018). "In particular, seven genes that were upregulated in the absence of NLRC5 during infection were identified by this analysis as playing a direct or indirect role in the upregulation of the NFκB signaling pathway." (PMID 32509599, 2020). "NLRC5 KD cells showed significant reduction in virus replication compared to the wild type (scramble control) cells in both the H5N2 and H5N1 infections albeit to a greater level in the low pathogenicity H5N2 infection." (PMID 32509599, 2020). "NLRC5, which can act as a negative modulator of inflammatory pathways, is critical for LPS-induced IL-10 production in macrophages, which upregulated in PmCQ2 infection, which suggests it might contribute to the lower inflammatory reaction in PmCQ2 infection." (PMID 32851030, 2020). "Infection of human fibroblasts with HCMV, but not heat-inactivated virus, induced NLRC5 mRNA within 24 h following infection and knockdown of NLRC5 impaired the upregulation of interferon alpha (IFN-α) in response to HCMV." (PMID 24671169, 2014).
bacterial infections (5 papers, 2017 to 2023). "However, there are few studies on NLRC5 and bacterial infections of the CNS." (PMID 34220868, 2021). "Moreover, NLRC5 deficiency does not influence cytokine induction by virus and bacterial infections." (PMID 34513725, 2021).
immune diseases (4 papers, 2019 to 2024). "In the past decades of years, researchers have made much progress in characterizing the NLRC5 crystal structure and detecting the expression of NLRC5 in tissues and cells of immune disease." (PMID 31824312, 2019). "Together with its broad participation in the occurrence and development of immune diseases, NLRC5 can be consequently treated as a potential therapeutic target." (PMID 31824312, 2019). "On one hand, some exploratory research has revealed that NLRC5 mRNA expression decreased slightly in immune diseases." (PMID 31824312, 2019). "In short, these findings indicated that NLRC5 was involved in the occurrence and development of immune disease through regulation of diverse signaling pathways." (PMID 31824312, 2019). "The fact that NLRC5 plays an essential role in the control of the regulatory mechanism has made it a promising therapeutic target for immune disease." (PMID 31824312, 2019). "On the other hand, several studies have also shown that the mRNA expression of NLRC5 increased dramatically in human and mouse immune tissues of immune disease, including bone marrow, lymph nodes, thymus, and spleen." (PMID 31824312, 2019). "Meanwhile, accumulating evidence suggested that NLRC5 plays vital regulatory role in the occurrence and development of immune diseases." (PMID 31824312, 2019). "NLRC5 (nucleotide-binding oligomerization domain-like receptor family caspase recruitment domain containing 5) has been reported to participate in various immune disorders, but its role in neurodegenerative diseases remains unclear." (PMID 37072793, 2023). "In addition, recent advance about immanent characteristics, biological function of NLRC5 and molecular mechanisms of NLRC5-mediated immune diseases are also discussed." (PMID 31824312, 2019). "Taken together, these evidences indicated that NLRC5 methylation plays a key role in immune diseases by regulating multiple biological pathways, and it could act as a promising biomarker as well." (PMID 31824312, 2019). "Therefore, it is necessary to put on a deep insight on the relationship between the immune function of NLRC5 and human immune diseases." (PMID 31824312, 2019). "However, the evidence for higher expression of NLRC5 in immune disease still remains controversial." (PMID 31824312, 2019). "In addition, NLRC5 could modulate immune response through many signaling pathways that have already been confirmed to participate in the occurrence and development of immune diseases for and wide." (PMID 31824312, 2019). "Moreover, there are few studies on the role of NLRC5 in human immune diseases." (PMID 31824312, 2019).
renal diseases (4 papers, 2018 to 2021). "Collectively, the NOD2 and NLRC5 showed proinflammatory effects in some renal diseases, and our results revealed a potential association between the NLRs and the development of AAV." (PMID 31186034, 2019).
cardiovascular disease (3 papers, 2019 to 2020). "Two of the proteins in the NLRC5 network (CD163 and FCGR3B) were also linked to cardiovascular diseases." (PMID 31900413, 2020).
heart disease (2 papers, 2019 to 2021). "In conclusion, these evidences indicated that the level of NLRC5 expression is closely related to heart disease." (PMID 31824312, 2019).
infectious disease (1 paper, 2012). A disorder directly resulting from the presence and activity of a microbial, viral, or parasitic agent in humans. "Future studies will further clarify the roles of NLRC5 and other NLRs in infectious diseases of chickens and may increase the efficacy of antiviral vaccine design." (PMID 22401171, 2012).
neurological diseases (1 paper, 2021). "In summary, the findings from studies on NLRC5 provide new insights into the pathogenesis and treatment of various neurological diseases." (PMID 34220868, 2021).
psychiatric disorder (1 paper, 2023). A disorder characterized by behavioral and/or psychological abnormalities, often accompanied by physical symptoms. "Recently, a transcriptomic study on psychiatric diseases revealed that Nlrc5 was highly expressed in the brains of patients, and we also found increased Nlrc5 expression in the hippocampal region of depressive mice." (PMID 37686068, 2023).
NLRC5 also shares sentences with these, for which no sentence is quoted: head/neck cancer (3 papers); alcohol (2); bladder cancer (2); Cerebral ischemia (2); chronic kidney disease (2); esophageal squamous cell carcinoma (2); gastric cancer (2); Liver Diseases (2); systemic lupus erythematosus (2); Abdominal obesity (1); acute myocardial infarction (1); Anxiety (1); asthma (1); Autoimmunity (1); central nervous system disorder (1); cervix tumors (1); Chronic colitis (1); Cirrhosis (1); Crohn disease (1); endometrial tumors (1); enterocolitis (1); follicular lymphoma (1); gastritis (1); Helicobacter infection (1); Hypertension (1); leiomyoma (1); Listeria monocytogenes infection (1); lung (1); macrophage activation syndrome (1); mammary adenocarcinoma (1).
A further 19 diseases each share a sentence with NLRC5 in 1 paper.